RIPK1 (receptor interacting serine/threonine kinase 1)
Diseases named in the same sentence as RIPK1 in open-access papers (continued):
Sharing a sentence is not in itself a finding about the gene and the disease.
Renal insufficiency (1 paper, 2025). A reduction in the level of performance of the kidneys in areas of function comprising the concentration of urine, removal of wastes, the maintenance of electrolyte balance, homeostasis of blood pressure, and calcium metabolism. "Our team has been investigating RIPK1/RIPK3 and its role in necrotic apoptosis for years, and our previous study showed that the RIPK1 antagonist Cpd-71 prevents cisplatin-induced renal insufficiency by reducing necroptosis and inflammation." (PMID 40351427, 2025).
retinal disease (1 paper, 2025). "In sharp contrast, both RIPK1 and RIPK3 proteins were detected within MCMV-infected of wildtype MAIDS-10 mice, as well as MCMV-infected eyes of MAIDS-10 mice deficient in either NLRP3, NLRP1b, or AIM2, all of which exhibited an atypical pattern of retinal disease." (PMID 41011779, 2025).
Rickettsia infection (1 paper, 2025). "Transcriptomic analysis further reveals that Rickettsia infection upregulates the host tumor necrosis factor (TNF) and NF-κB signaling pathways, which subsequently suppress RIPK1 kinase activity and contribute to the inhibition of host cell death." (PMID 40607949, 2025).
Sandhoff disease (1 paper, 2021). A lysosomal disorder from the GM2 gangliosidosis family, caused by biallelic pathogenic variants in the HEXB gene, characterized by GM2 ganglioside accumulation in the nervous system and progressive central nervous system degeneration. "In Sandhoff disease, another sphingolipid disorder, neuroinflammation, accumulation of p62 and increased Ripk1 expression was observed." (PMID 34172992, 2021).
sarcoma (1 paper, 2020). A usually aggressive malignant neoplasm of the soft tissue or bone. "To determine whether Ripk1‐induced cell death of BN175 sarcoma cells is capable of mobilising the immune system, we profiled infiltrating immune cell populations post‐therapy." (PMID 32419365, 2020). "To evaluate the possibility of harnessing RIPK1's cytotoxic potential during ILP, we combined the current standard‐of‐care treatment regimen (ILP‐TNF/Mel) with pharmacological inhibitors of IAPs (SM) and evaluated its efficacy in an immune‐competent rat model of extremity sarcoma (ESTS)." (PMID 32419365, 2020). "To evaluate the possibility of harnessing RIPK1's cytotoxic and immunogenic potential during ILP‐based and TNF‐mediated treatments in combination with SM, we employed a syngeneic, immune‐competent rat model of ILP‐TNF/Mel using the syngeneic BN175 sarcoma cell line in Brown Norway rats." (PMID 32419365, 2020).
sarcopenia (1 paper, 2025). Progressive decline in muscle mass due to aging which results in decreased functional capacity of muscles. "However, Ripk1-Cd4-Cre mice (Ripk1ΔCD4) developed age-related inflammatory disorders in the lungs, kidneys and heart, as well as sarcopenia and neurodegeneration, suggesting that RIPK1’s role in T cells is crucial for maintenance of tissue homeostasis in various tissues." (PMID 40307618, 2025).
selenium deficiency (1 paper, 2023). A nutritional deficiency disease resulting from inadequate selenium levels in the body, which can lead to impaired function of selenoproteins essential for antioxidant defense and thyroid hormone metabolism. "The high level of expression of c-FLIP, MLKL, RIPK1, and RIPK3 indicated that necroptosis also causes lung damage during selenium deficiency." (PMID 37107171, 2023).
serous ovarian cancer (1 paper, 2018). "We found that the expression of RIPK3, but not that of RIPK1, was progressively reduced during xenograft tumor growth in four out of five PDX samples derived from high-grade serous ovarian cancer biopsies." (PMID 30157175, 2018).
status epilepticus (1 paper, 2025). Status epilepticus is defined as a continuous seizure lasting more than 30 min, or two or more seizures without full recovery of consciousness between any of them. "The results show that pharmacological inhibition of necroptosis using Nec-1s, a specific inhibitor of RIPK1, or selective inhibition of soluble TNFα by XPro1595, as well as genetic knockout of TNFR1, effectively rescued CA1 astrocyte loss caused by kainate-induced status epilepticus." (PMID 40629542, 2025).
Stevens-Johnson syndrome (1 paper, 2026). Stevens-Johnson syndrome is a limited form of toxic epidermal necrolysis characterized by destruction and detachment of the skin epithelium and mucous membranes involving less than 10% of the body surface area. "Necroptosis has been implicated in the pathogenesis of Stevens-Johnson syndrome and toxic epidermal necrolysis (SJS/TEN), with prior studies demonstrating tissue-level involvement of receptor-interacting protein kinases RIPK1 and RIPK3." (PMID 42193144, 2026).
temporal lobe epilepsy (1 paper, 2025). A localization-related (focal) form of epilepsy characterized by recurrent seizures that arise from foci within the temporal lobe, most commonly from its mesial aspect. "KEY POINTS: In the early stage of experimental temporal lobe epilepsy with hippocampal sclerosis (TLE-HS), we observed activation of RIPK1, RIPK3 and MLKL in CA1 astrocytes, along with a reduction in astrocyte density, providing evidence for necroptotic cell death." (PMID 40629542, 2025).
transient cerebral ischemia (1 paper, 2019). "Interestingly, we found that transient cerebral ischemia could significantly activate RIPK1 kinase as indicated by increase of p-RIPK1 (Ser 166) in injured brain tissues." (PMID 31440386, 2019).
VEXAS syndrome (1 paper, 2024). An adult-onset inflammatory disease that affects only males and is caused by somatic, not germline, mutations. "Plasma levels of lactate dehydrogenase (LDH), a marker of necrosis and cellular injury, correlated with VEXAS syndrome, as well as RIPK1 and RIPK-3, a key kinase involved in programmed necroptosis and inflammatory cell death." (PMID 38291039, 2024).
Yersinia enterocolitica infection (1 paper, 2023). "We also demonstrated previously that p38MAPK/MK2 pathway repressed cell apoptosis via RIPK1 in an Yersinia enterocolitica infection model." (PMID 37771590, 2023).
tumor (210 papers, 2013 to 2026). "The cancer-associated dysregulation of RIPK1 exhibits tumour type-specificity, hijacking survival and death related signalling networks to accelerate tumour progression." (PMID 41334873, 2025). "In vivo studies further demonstrate that either overexpression of RIPK1 or the D324K mutation significantly attenuates tumor progression and prolongs survival." (PMID 41267084, 2025). "The loss of a RIPK1 pro-survival checkpoint in sensitized tumor cells is particularly informative given that these cells undergo T cell-induced, RIPK1-dependent apoptotic cell death." (PMID 41315176, 2025). "An elevated expression of RIPK1 was observed in both malignant epithelial cells and tumor-associated macrophages within human pancreatic ductal adenocarcinoma (PDA)." (PMID 38576612, 2024). "Further, a novel CHOP activator LGH00168 exhibited anti-tumor activity in A549 cells and mice bearing lung tumor xenografts via ROS-mediated loss of ∆ψM, ER stress, NF-κβ inhibition, and RIPK1-dependent necroptosis." (PMID 36361505, 2022). "In line with this, administration of RIPK1 inhibitor significantly suppressed tumor growth and development in colitis-associated cancer." (PMID 39872161, 2022). "In osteosarcoma, overexpression of miR-155-5p has been reported as the mechanism leading to the inhibition of RIPK1 expression and was associated with poor prognosis and increased tumor growth." (PMID 34490126, 2021). "In this study, RIPK1 was demonstrated to be upregulated in immunosuppressive tumor-associated macrophages (TAM)." (PMID 34490126, 2021). "Enhanced tumor susceptibility to RIPK1-dependent death promotes T cell–derived, TNF-dependent tumor destruction." (PMID 34752416, 2021). "Factors include differences in genetics, epigenetics, and mutational burden across solid tumors, as well as genes and networks associated with expression of caspases, RIP3K and RIPK1, inflammasomes, and redox status of the tumor cell." (PMID 33003477, 2020). "Taken together, these results show that RIPK1 or RIPK3-deficient ECs fail to respond to tumor-induced vascular permeability or VEGF-A-induced permeability and angiogenesis, resulting in a defect in B16-F10 transendothelial migration." (PMID 28151480, 2017). "Loss of the kinase activity in RIPK1, a member of the necrosome also reduced tumor nodules in the lung by 38%." (PMID 28151480, 2017). "Consequently, tumor cells experiencing a loss of TNF-induced RIPK1 S25 phosphorylation exhibit increased RIPK1 activation and fail to recruit non-canonical IKK kinases (TBK1 and IKKε) to the TNFR1 complex." (PMID 41315176, 2025). "Four of 13 overlapped markers (MXRA8, CLMP, VCAN and FBLN1) are involved in cell adhesion and tumor metastasis, suggesting that dysfunctions in cell adhesion pathways could lead to anti-PD-1 resistance associated by RIPK1 and AXL." (PMID 36518525, 2022). "While many studies have demonstrated that necroptosis-mediated inflammatory cell death can promote antitumor immune responses, it has also been reported that RIPK1 activity regulates tumor immunity by reprogramming tumor-associated macrophages in some cancers, independent of RIPK3157,182." (PMID 36171264, 2022). "Indeed, inhibition of RIPK1 kinase activity has been displayed to enhance antitumor immunity through modulation of tumor-associated macrophages." (PMID 33567618, 2021). "To address this, we employed in vitro systems and murine models of T cell–dependent transplant or tumor rejection in which target cell susceptibility to RIPK1-dependent cell death could be genetically altered." (PMID 34752416, 2021).
tumor (continued). "Genetic loss of TNF and its death-signaling molecules (e.g., Tnfr1 and Casp8) led to uncontrolled tumor growth, whereas loss of molecules involved in ubiquitinating RIPK1 (e.g., Traf2 and Birc2/3) resulted in tumor rejection following immune checkpoint blockade." (PMID 34752416, 2021). "Furthermore, disruption of heat shock protein 90 (Hsp90) function by geldanamycin causes RIPK1 degradation, which sensitizes tumor cells to TNF-induced apoptosis." (PMID 25790448, 2015). "Recent studies have demonstrated that the inhibition of RIPK1 kinase activity enhances antitumor immunity by modulating tumour-associated macrophages (TAMs), indicating that RIPK1 may serve as a promising immunomodulatory target for the development of innovative anticancer therapies." (PMID 41334873, 2025). "Our data provide a likely explanation as to why loss of Casp8 and low levels of Ripk1 can be driver mutations in certain types of cancer, leading to chromosome instability that may favor tumor evolution, heterogeneity, acquisition of drug resistance, and heightened risk for tumor relapse." (PMID 30598363, 2019). "Deletion of Ripk1 or Mlkl in tumour cells, or Mlkl in the stromal compartment, markedly impairs therapeutic efficacy." (PMID 41792126, 2026). "We demonstrate that the anti-CD47 antibodies SRF231, magrolimab, and B6H12 eliminated tumor cells from various in vitro and in vivo lymphoid malignant models via the activation of the RIPK1/MLKL/necroptotic pathway." (PMID 41484790, 2026). "In conclusion, our findings indicate that CL-387785 induces necroptosis in tumor cells via the TRADD/RIPK1/NF-κB/CD80 signaling pathway, thereby sensitizing tumors to anti-PD-1 therapy." (PMID 41694588, 2026). "Detailed mechanistic studies indicated that CL-387785 targets TRADD, recruiting RIPK1 to induce necroptosis in tumor cells, with subsequent nuclear translocation of NF-κB, which regulates CD80 transcription." (PMID 41694588, 2026). "In this review, we summarise the biological functions of RIPK1 and elaborate on its roles in cancer progression in terms of the tumour immune microenvironment, tumour metastasis, and chemoresistance." (PMID 41334873, 2025). "Alterations at the genetic, epigenetic and expression levels collectively enable RIPK1 to promote tumour metastasis, immune evasion, and therapy resistance." (PMID 41334873, 2025). "Based on this, we developed a combination therapy of SM164 and sunitinib for tumor types with high expression of SPOP/RIPK1." (PMID 41122967, 2025). "A similar trend was observed in the immunostaining for RIPK1 and Beclin, where increased expression of necrotic markers in tumor tissue was noted under controlled autophagy activation compared to control mice." (PMID 39910335, 2025). "Studies have shown that radiation therapy significantly upregulates the expression of MLKL in tumor cells and activates the RIPK1/RIPK3/MLKL axis through the ZBP1‐mediated pathway, directing tumor cells to undergo necroptosis." (PMID 41287826, 2025). "This functional duality underscores the complexity of targeting RIPK1, necessitating intervention strategies tailored to tumour type, death pathway status, and individualised immune microenvironment features." (PMID 41334873, 2025). "TRAF6 directly ubiquitinates and degrades RIPK1, inhibiting both necroptosis and apoptosis, thereby promoting cancer cell proliferation and tumor progression." (PMID 41267084, 2025). "Significant differences in the expression of genes related to cellular dedifferentiation, proinflammatory cell death pathways, and tumor-infiltrating immune cells were found between high- and low-RIPK1 expression groups." (PMID 40565018, 2025).
tumor (continued). "Activation of cell necroptosis mediated by the enzymatic activity of intra-tumoral RIPK1 enhances tumour ICD." (PMID 41334873, 2025). "Upon TNF-α signaling, pharmacologic inhibition of TAK1 sensitized tumor cells to RIPK1-dependent apoptosis." (PMID 41102176, 2025). "Studies have shown that LD4172 exhibits high-efficiency RIPK1 degradation activity both in vitro and in vivo, significantly enhances tumor immune responses, and sensitizes tumors to anti-PD-1 therapy." (PMID 40301325, 2025). "Under the stimulation condition of the supernatant of HER2 + IBC tumour cells, the results of the WB experiment can also confirm that RIPK1-mediated MLKL phosphorylation is involved in this process." (PMID 40624675, 2025). "RIPK1 was significantly upregulated in tumour cells of immune checkpoint blockade (ICB)-resistant murine models, where it drives TME immunosuppression by recruiting suppressive myeloid cells and impairing cytotoxic lymphocyte infiltration." (PMID 41334873, 2025). "Decreased levels of these kinases align with our observations of decreased RIPK1 S25 phosphorylation following T cell treatment in sensitized tumor cells, indicating that loss of checkpoint kinase recruitment to complex I may be a putative mechanism driving tumor sensitivity to T cell attack." (PMID 41315176, 2025). "The RIPK1/RIPK3/MLKL signaling cascade constitutes a central axis governing necroptotic cell death in tumor biology." (PMID 41180485, 2025). "We next evaluated protein expression profiles using data from the Clinical Proteomic Tumor Analysis Consortium, which confirmed elevated RIPK1, RIPK3, and MLKL protein abundance in GBM relative to normal tissue." (PMID 41429922, 2025). "CD8 T cells rely on cytokines such as TNF to carry out their cytotoxicity against tumors, and recent findings link select tumor mutations in the TNF pathway to increased T cell killing, in a manner dependent on RIPK1 kinase." (PMID 41315176, 2025). "SPOP and RIPK1 were substantially overexpressed in tumor tissues, while RIPK3 expression was reduced." (PMID 41122967, 2025). "As reported in the study, the RIPK1 degrader LD4172 can serve both as a chemical probe to investigate the scaffolding function of RIPK1 and as a potential therapeutic agent to increase tumor response to ICIs therapy." (PMID 41247642, 2025). "In tumour cells, RIPK1 suppresses immunogenic cell death, promotes an immunosuppressive tumour microenvironment, which facilitates immune evasion, metastatic progression, and therapeutic resistance, contributing to an immunologically cold tumour phenotype." (PMID 41334873, 2025). "Given that sunitinib and SM164 cotreatment effectively induced RIPK1-positive tumor cell death in vitro, their combined effect was then investigated in vivo using a xenograft mouse model." (PMID 41122967, 2025). "Despite these research advancements, the mechanistic basis for RIPK1’s paradoxical roles remain poorly defined, particularly how tumour-intrinsic factors (e.g., oncogenic drivers) and extrinsic cues (e.g., cytokine milieu) dictate its functional dichotomy." (PMID 41334873, 2025). "Inhibition of RIPK1/3 via genetic or pharmacological means can halt cell proliferation, metastasis, and tumor progression." (PMID 41584509, 2025). "Building on these insights into the tumor immune microenvironment, the selective RIPK1 inhibitor GSK0547 has shown significant antitumor efficacy in preclinical models." (PMID 41267084, 2025). "This approach is crucial for elucidating the distinct roles of RIPK1 across different cellular subpopulations (e.g., tumour cells, immune cells) and for establishing predictive biomarkers." (PMID 41334873, 2025). "In STSs, NK cells can be activated by RIPK1‐induced immunogenic cell death of tumor cells, contributing to tumor control." (PMID 41357670, 2025).